IL6 (interleukin 6)
Diseases named in the same sentence as IL6 in open-access papers (continued):
Sharing a sentence is not in itself a finding about the gene and the disease.
COVID-19 (continued). "Hyperbaric oxygen treatment reduces the expression of L-1β, IL-6, and TNF-α, was shown to be effective in the treatment of radiation injury and wound-healing, and has been proposed as a treatment option to prevent the development of post-COVID-19 fibrosis." (PMID 36559025, 2022). "We found lower lymphocyte counts and interleukin-1R levels and higher levels of C-reactive protein, interleukin-6, and interleukin-8 in severe compared than in non-severe COVID-19 patients." (PMID 35687545, 2022). "Significantly elevated levels of inflammatory cytokines TNF-α, IL-1, IL-6, and IL-10 have been documented in cases of severe COVID-19 compared to cases of non-severe disease." (PMID 36282812, 2022). "TNF-, IL-2, IL-6, IL1B, IL7, IL10, IFN-, GCSF, CXCL10, CCL2, ferritin, D-dimer, fibrinogen, leukocytosis, and C-reactive protein (CRP) levels are significantly higher in critically ill COVID-19 patients." (PMID 35645351, 2022). "Here, we proposed the use of a rapid IL-6 test strip which contains a lateral flow immunoassay (LFA)-based kit accompanied by a handheld optical reader that, in combination, is well suited for recognizing acute respiratory failure among COVID-19 patients." (PMID 35242747, 2022). "In children, epithelial cell proportions did not change but in the immune compartment IL6+ monocytes were significantly enriched in COVID-19, with a trend towards higher CXCL10+ monocytes and neutrophils." (PMID 34937051, 2022). "Attenuating the IL-6, IL-33 and DAMP pathways while administering IL-1ra, IL-33r and, potentially, recombinant IL-38, seems to be the most promising strategy to combat severe COVID-19." (PMID 35563282, 2022). "Three key pathways (pathways in cancer, the TNF signaling pathway, and lipid and atherosclerosis) and the top six anti-COVID-19 core targets (IL-6, PPARG, MAPK3, PTGS2, ICAM1, and MAPK1) were determined to be involved in the treatment of COVID-19 with active phytomolecules of Kochiae Fructus." (PMID 35992697, 2022). "According to the key role of IL-6 in CSS, several mAb drugs have been considered for the treatment of severe COVID-19, including sarilumab (Kevzara), tocilizumab (Actemra) and levilimab, which target IL-6R, as well as clazakizumab, siltuximab and olokizumab, which target IL-6." (PMID 34983527, 2022). "Our clinical obeservation indicated that the patient B showed low level of cytokines such as IL-6, MCP-3, MCP-1, IP-10 and IL-1α after treatment with LS, which hinted that LS could prevent COVID-19 into hyperinflammatory status." (PMID 35365215, 2022). "This evidence underpins the current hypothesis that NOX is an essential regulator in COVID-19 pathogenesis, and that blocking the expression of NOX might hinder the production of ATII-induced ROS and IL-6, minimising inflammation and tissue injury." (PMID 35639261, 2022). "In this context, it is not surprising that even high IL-6 serum concentrations have been correlated to disease COVID-19 severity." (PMID 35584141, 2022). "Early routine blood biomarkers could be key predicting factors of COVID-19 morbidity and mortality as suggested for C-reactive protein (CRP), IL-6, prothrombin and D-dimer." (PMID 35054342, 2022). "The concentrations of anti-N IgG, IgG total, IgG4 and IL-6 were elevated in the COVID-19 group in comparison to the vaccinated and non-vaccinated controls." (PMID 36232891, 2022). "We aim to investigate the diagnostic accuracy and prognostic utility of the inflammatory biomarkers (IL-6, CRP, PCT, ferritin, and leukocytes) to predict hospitalisation and outcome in cases with COVID-19 and compare them with cases with respiratory infections other than COVID-19." (PMID 35622838, 2022). "CRP, IL-6, D-dimers, fibrinogen, and ferritin were significantly different after comparing survivors with non-survivors and non-severe with severe COVID-19 patients." (PMID 35207531, 2022).
COVID-19 (continued). "Thus, ACE2 plays an important role in inflammation, and its down-regulation may aggravate COVID-19 via the renin-angiotensin system, including by promoting pathological changes in lung injury and involving inflammatory responses in conjunction with the release of cytokines, especially IL-6." (PMID 35053224, 2022). "In COVID-19-induced ARDS, IL-6 levels are correlated with disease-related mortality." (PMID 35055050, 2022). "With the exception of IL-1β and TNF-α, HIV/COVID-19 patients showed similar levels of IL-6 and IL-8 than those observed in HIV patients without COVID-19." (PMID 35891555, 2022). "In addition, peripheral blood immune cells from severe COVID-19 patients exhibit diminished type I and III IFN responses but enhanced proinflammatory IL-6 and TNF-α responses." (PMID 35832809, 2022). "Inflammatory parameters (IL-6, CRP; IL-6/Ly ratio) are significantly elevated in non-survivor critically-ill patients with COVID-19." (PMID 36142336, 2022). "Among COVID-19 patients admitted to the hospital, IL-6 was higher in the non-survival group than in the survival group." (PMID 35204599, 2022). "However, no previous studies postulated the effect of age on the levels of inflammatory mediators including IL-6 and TNF-α in COVID-19 patients." (PMID 36381078, 2022). "Severe COVID-19 patients showed impaired IFN-1 signaling compared to mild patients, and developed an inappropriate inflammatory state due to early delay in IFN-1 expression and activation of pro-inflammatory cytokines (IL-1, IL-6, IL-8, MCP-1, and CXCL-10)." (PMID 35185933, 2022). "Our results indicated that serum IL-6 levels were not elevated in nonsevere COVID-19 cases compared to healthy controls (P = 0.13), while IL-6 levels were elevated in severe patients compared to healthy controls (WMD = 25.05, 95% CI: 6.92-43.17, and P < 0.01)." (PMID 35540724, 2022). "The immunological feature of severe COVID-19 could be defined by the “core signature” cytokines in cluster 2: MCP-3, IL-6, IFN-γ, and CXCL10, which strongly correlated with each other and CRP, and are involved in cytokine release storm." (PMID 35350784, 2022). "Analysis of an independent cohort of 108 patients from a different center (Cohort 2) demonstrated feasibility of CC/miRNA profiling in leftover hospital blood samples with similar severe disease CC and miRNA profiles, and revealed CCL20, IL6, IL10, and miR-451a as key correlates of fatal COVID-19." (PMID 34957382, 2022). "None of these factors – with the exception of IL-6 – were important predictors of mortality in studies with large numbers of markers regarding COVID-19 in the general population." (PMID 36700209, 2022). "Increased IL-6 levels have been found in serum of patients with hyposmia; whereas researchers in Turkey found that serum IL-6 level was lower in patients with COVID-19 related anosmia than those without anosmia." (PMID 36419783, 2022). "Receiver operating characteristic curves of MLR, NLR, SII, SIRI, AISI, IL-6, and TSS were created to determine whether the baseline of these markers was predictive of IMV need, mortality, and common endpoint in patients with COVID-19." (PMID 36140490, 2022). "Clearly, combined action of YMP with specific durations might be effective in reducing IL-6, cortisol, and TNF-α among the COVID-19 patients." (PMID 36248417, 2022). "Particular attention should be paid to IL-6, because it is suspected to play a key role in the pathogenesis of AP as well as acute respiratory distress syndrome (ARDS) that is the most common and most severe clinical manifestation of COVID-19." (PMID 35055050, 2022). "The lymphocyte level was lower, while the levels of NLR, LDH, CRP, IL-6, and IL-8 were higher in patients with severe COVID-19 than in those with non-severe symptoms." (PMID 35687545, 2022). "In another study, IL-6 was found to be 1.7-times higher in nonsurvivor COVID-19 patients than survivors." (PMID 35059221, 2022).
COVID-19 (continued). "Together with proinflammatory cytokines TGF-β, VEGF, IL-6 and TNF-α, this may lead to PF in COVID-19." (PMID 36268783, 2022). "The data were collected at the beginning of the pandemic when steroids and IL-6 inhibitor biologics were not widely used in patients with COVID-19." (PMID 35736068, 2022). "However, children with MIS had higher rates of GI symptoms than children with primary COVID-19, as well as increased zonulin, LBP, and IL-6 in the early stage of MIS-C." (PMID 36032119, 2022). "Similarly, high levels of IL-6 and CCL5 (RANTES) as well as viremia and decreased CD8+ T cells are found in terminal COVID-19 patients." (PMID 35062298, 2022). "The IL-6, IL-1β, TNF-α, and IL-10 levels were consistently upregulated in patients with COVID-19." (PMID 36230930, 2022). "In addition, IL-1β, IL-4, IL-6, IL-18, IL-35, PGE2, and TXA2 levels in moderate and severe COVID-19 patients were significantly higher (p < 0.001) than in healthy controls." (PMID 36298501, 2022). "Amongst the COVID-19 patients, greatly elevated levels of inflammatory cytokines/chemokines were detected in respiratory samples across ETA, sputum and BAL specimens, with concentrations being 160× (MCP-1), 90× (IL-6) and 110× (IL-8) higher than in plasma." (PMID 35589689, 2022). "It has been observed that severe COVID-19 present low expression of HLA-DR on monocytes in correlation with ICU (Intensive Care Unit) need, probably due to the antagonizing action of IL-6." (PMID 35336077, 2022). "As expected, significantly increased activation of pro-inflammatory cytokines (IL-1α, IL-2Ra, IL-6, IL-8, and IL-18) in fatal COVID-19 compared to non-fatal COVID-19 sera was measured." (PMID 35386707, 2022). "Previous research has reported a significant difference of interleukin-6 (IL-6) levels between severe COVID-19 patients and non-severe COVID-19 patients." (PMID 35215138, 2022). "In this regard, certain blood biomarkers such as IL-6, ferritin, D-dimer, and CRP may be able to anticipate the development of the cytokine storm leading to COVID-19 complications." (PMID 36741367, 2022). "Several other clinical risk factors associated with COVID-19 RP have been previously documented, such as age, LYM count, IL-6, AST, and D-dimer, which were not confirmed in our study." (PMID 35755819, 2022). "A significant expansion of CD14+CD16+ monocytes featuring high expression of IL-6 in the blood discriminated patients with COVID-19 admitted to ICUs from those who did not require intensive care." (PMID 34367190, 2021). "This review points to lymphopenia, thrombocytopenia, neutrophilia, leukocytosis as well as increased levels of IL-6, ferritin, D-dimer, aspartate aminotransferase, lactate dehydrogenase, procalcitonin, creatinine and CRP as indicators of severe and fatal cases of COVID-19." (PMID 34185801, 2021). "In addition, based on two cases of patients with depression after COVID-19, an association between depression and interleukins, including IL-6, was demonstrated independent of other factors, which may justify the administration of cytokine-reducing drugs to prevent depression after COVID-19." (PMID 34685427, 2021). "IL-6 was the most robust predictor of infection and discriminated moderate COVID-19 patients from healthy controls, regardless of epidemic peak curve." (PMID 34675240, 2021). "Moreover, in vitro, higher levels of IL-6, TNF-α and IL1-β were released from monocytes derived from COVID-19 patients compared to H1N1 2009 patients." (PMID 34728719, 2021). "There were no cellular components with IL6 involvement among the first five cellular components in which the junction targets of COVID-19 and LHQW were included." (PMID 34731090, 2021). "Considering the objectives of our study, we highlight that there were significant, direct correlations between CCl2, galectin-3, PON1 concentration, CRP, IL-10, IL-6, and angiotensin II in COVID-19 positive patients, but not in the COVID negative ones." (PMID 34205807, 2021).
COVID-19 (continued). "Indeed, studies have demonstrated the presence of elevated levels of inflammatory factors such as interleukin-6 (IL-6), tumor necrosis factor-α (TNF-α), and IL-1β, in patients with COVID-19." (PMID 34444014, 2021). "LH works through the suppression of viral loads in the cytoplasm and cellular membrane and replication of COVID-19 and H1N1 and can inhibit the release of tumor necrosis factor-alpha (TNF-α), interleukin-6 (IL-6), and macrophages, all of which are components in the cytokine storm." (PMID 34831757, 2021). "However, in a longitudinal study of one patient with protracted COVID-19 (over 3 weeks), a 4-fold BALF to blood gradient for IL-6 was attained just days before death." (PMID 34178722, 2021). "In agreement with other studies, we found that inflammatory cytokines are elevated in hospitalized COVID-19 patients compared with HC [median (IQR), all units picograms per milliliter: IL-6 4.65 (3.32–9.16) vs 0.69 (0.55–0.89), p < 0.001; TNFα 4.49 (1.87–8.03) vs 0.04 (0.04–0.84), p < 0.001]." (PMID 34792686, 2021). "Interestingly, in wave 2, only IL-1ra, IL-2, IL-6 IL-8 and IFN-γ concentrations were significantly higher in serum of mild and severe COVID-19 patients compared to controls." (PMID 34675240, 2021). "Consistent with earlier reports, the results of our present analyses revealed that the amount of IL-6 in the sera clearly increased in all 10 of the severe/critical COVID-19 patients, but not in the asymptomatic patients." (PMID 33575497, 2021). "Finally, IL-6, MAPK3, MAPK1, MAPK14, MAPK8, IL-1β, CCL2, EGFR, PPARG, and NOS2 were declared key targets of XFBD for COVID-19." (PMID 35185537, 2021). "Measurement of IL-6 levels and viral RNA load may also restrict the use of ECMO as well as ventilator in COVID-19 by guiding anti-viral or immunomodulatory therapies." (PMID 34379684, 2021). "In the initial phase of the infection, COVID-19 is thought to antagonize type I INF response in the alveolar epithelial cells of the patient’s airways, leading to rapid viral replication and subsequent activation of numerous inflammatory markers, namely IL-6." (PMID 34177298, 2021). "So far, many studies have demonstrated that high levels of circulating IL-6 closely relate to negative clinical course of COVID-19 patients." (PMID 34379684, 2021). "Accordingly, ENV is strongly expressed in blood cells of COVID-19 patients but not in healthy donors, and its level correlates with inflammatory mediators (IL-6, IL-17, and CXCR1), and with markers of T-cell exhaustion (e.g., PD1)." (PMID 34646278, 2021). "In this single-center study of 160 consecutive critically ill COVID-19 patients with moderate to severe ARDS demanding high oxygen flow, serum albumin, IL-6, and D-dimer at admission to ICU, accompanied by a chest CT severity score, were marked as independent predictors of mortality." (PMID 33968298, 2021). "Higher blood levels of inflammatory biomarkers (e.g. CRP) and cytokines (e.g. IL2, IL7, IL10, etc.)have been reported in COVID-19 patients admitted to the ICU3, and IL6 and IL10 have been determined to be strong discriminators for severe disease and death, consistent with our findings." (PMID 33627696, 2021). "HuR may also be involved in the pathogenesis of COVID-19 by its ability to increase inflammation, as SARS-CoV-2 infection induces TNF-α, IL-6, and CC-chemokine ligand 2 (CCL2)." (PMID 35011584, 2021). "Clinical studies have shown elevated inflammatory cytokines, including tumor necrosis factor-alpha (TNF- α), interleukins (IL; IL2, IL6, IL7, IL8, IL9, and IL10), chemokines (CXCL10, CCL2, IP10, MCP1), and colony-stimulating factors (G-CSF, GM-CSF) in COVID-19 patients compared to a healthy person." (PMID 34513735, 2021). "The cytokine profile of patients with severe COVID-19 is characterized by an increase of several cytokines, mainly (but not restricted to) IL-1β, IL-2, IL-6, IL-7, IL-8, and TNF-α." (PMID 33669218, 2021).
COVID-19 (continued). "Indeed, corticosteroids have been shown to suppress CRS, and NR3C1 has been shown to transcriptionally downregulate many inflammatory cytokines overexpressed in COVID-19 patients, such as CCL2, IL1B, and IL6." (PMID 34163359, 2021). "In a meta-analysis, the mean IL-6 level in severe COVID-19 patients was 2.9 fold higher than in non-severe patients, and elevated IL-6 was correlated with adverse clinical outcomes such as intensive care unit (ICU) admission, ARDS, and death." (PMID 34959657, 2021). "Third, we did not test biological data associated with COVID-19 prognosis (CRP, d-dimers, ferritin, interleukin-6, lymphocyte ratio)." (PMID 34779944, 2021). "Therefore, this network also displays the contribution of increased pro-inflammatory molecules or signaling pathways (IL1B, IL6, IL8, IL17a) and upregulated chemokine signaling (CXCR4 signaling, CCL5) observed in severe COVID-19 outcomes." (PMID 33941085, 2021). "While CXCL9, CXCL10 and CXCL11 expression levels were increased both in moderate and severe disease compared to healthy levels, IL1β, IL6, TNF as well as CCL2, CCL3, CCL4 and CCL7 were expressed at higher levels in lung macrophages from patients with severe COVID-19." (PMID 34367190, 2021). "Notwithstanding that the IL-6 levels in these patients continue to increase over time, the mechanism leading to its elevation in severe COVID-19 is not currently clear." (PMID 34912345, 2021). "Moreover, serum levels of IL-6 >80 pg/mL and hs-CRP >97 mg/L have been reported to identify correctly 80% of hospitalized COVID-19 patients requiring a ventilator with C statistic values of 0.90 and 0.97, respectively." (PMID 34111164, 2021). "In order to investigate the contribution of innate immune cells to the production of the most prominent cytokines expressed during COVID-19, we analyzed the production of pro-inflammatory IFN-α, TNF-α, and IL-6 by in vitro differentiated innate immune cells upon SARS-CoV-2 infection." (PMID 34122407, 2021). "Due to a lack of cases, the association between IL-6 and clinical outcome in patients with CHD and COVID-19 remains to be determined." (PMID 34123873, 2021). "In addition, previous clinical data revealed that IL-6 and TNF-α were the most critical cytokines detected in patients with severe COVID-19 symptoms." (PMID 35401158, 2021). "In hospitalized COVID-19-patients, low thiol plasma concentrations were correlated with the severity of the disease and demonstrated to be a promising tool to predict ICU admission, whereas IL-6 and calprotectin measurements effectively predicted mortality." (PMID 34299080, 2021). "• IL-6 levels follow the response to novel COVID-19 therapies, however do not offer a clinical advantage over C-reactive protein and bedside observations in predicting severe disease." (PMID 33815405, 2021). "In critically sick COVID-19, the cytokine release storm (CRS) has been mediated by IL-6." (PMID 34884440, 2021). "Recent published studies in adult populations have reported that elevated levels of inflammatory cytokines levels such as TNF-α, IL-1β, IL-6, IL-10, IL-17, IL-18, IFN-γ are seen in active COVID-19 individuals compared to seropositive individuals and healthy controls." (PMID 33813138, 2021). "Among all laboratory features, IL-6, high-sensitivity troponin I (hsTNI), and D-dimer had the most significant differences between nonsevere and severe COVID-19 types." (PMID 33714935, 2021). "Meta-analysis of mean IL-6 concentrations demonstrated 2.9-fold higher levels of IL-6 in hospitalized COVID-19 patients with complications compared to patients without complications." (PMID 33920604, 2021). "In our study in the severe COVID-19 group we observed high negative correlation between proportion of IL-6 level and eosinophils." (PMID 34064802, 2021).